ADAMTS13 (ADAM metallopeptidase with thrombospondin type 1 motif 13)
Diseases named in the same sentence as ADAMTS13 in open-access papers (continued):
Sharing a sentence is not in itself a finding about the gene and the disease.
COVID-19 (continued). "Comparisons between the two age groups within the COVID-19 (+) patients indicates that patients ≥65 years of age have a reduced plasma ADAMTS13 activity (remaining in the reference range), as well as increased VWF:AG, VWF:CBA, and VWF/ADAMTS13 activity ratio." (PMID 35087853, 2021). "The differences in VWF, ADAMTS13, thrombin generation, and plasmin generation parameters were evaluated in plasmas from COVID-19 (+) and COVID-19 (−) patients that were <65 and ≥65 years of age." (PMID 35087853, 2021). "Despite elevated VWF function in COVID-19 (+) patients' plasma, only mild changes in ADAMTS13 levels or activity are observed." (PMID 35087853, 2021). "Although there have been some COVID-19 data involving ADAMTS13 activity levels, the small sample size in these reports precluded any major conclusions." (PMID 33709050, 2021). "This retrospective analysis of acutely ill COVID-19 (−) and COVID-19 (+) patients suggests VWF/ADAMTS13 axis parameters, along with thrombin and plasmin generation, are relevant coagulation parameters to measure in early COVID-19 infection." (PMID 35087853, 2021). "Specifically, in the COVID-19 (+) group, median VWF:AG, VWF: CBA and VWF:AG/ADAMTS13 activity ratios increased (by 43, 23, and 21.5%, respectively) compared to the COVID-19 (−) group." (PMID 35087853, 2021). "A recent study demonstrated that ADAMTS13 activity was significantly associated with VTE onset and survival in COVID-19 patients." (PMID 34276770, 2021). "In the present study, COVID-19 (+) patient plasma showed normal ADAMTS13 functional activity (≥50%) and normal platelet levels (~250 × 109/L), consistent with prior studies of COVID-19 disease progression and severity." (PMID 35087853, 2021). "In Montreal, the epicenter of the pandemic in Canada, critically ill COVID-19 patients admitted to intensive care units had a median age of 62, with 67% being male, potentially increasing referrals for ADAMTS-13 activity testing among males in this age group in Quebec." (PMID 40993743, 2025). "Additionally, a substantial proportion of patients with COVID-19 developed autoantibodies to ADAMTS-13 during the course of the disease." (PMID 40993743, 2025). "The demonstration of both activated pathways, even in the absence of signs of TMA, could enhance the hypothesis that the complement activation and vWF/ADAMTS13 axis both contribute to the pathogenesis of COVID-19 coagulopathy." (PMID 40508203, 2025). "In this prospective monocentric observational study, we investigated whether COVID-19-associated coagulopathy meets the criteria for TMA and evaluated the roles of complement activation and vWF/ADAMTS13 imbalance in disease severity." (PMID 40508203, 2025). "We also statistically correlated high BMI, low ADAMTS13 activity, and poor COVID-19 outcome." (PMID 38608066, 2024). "Given that obesity may influence ADAMTS13 activity, it is feasible; however, it remains unclear whether ADAMTS13 activity acts as a mediator between obesity and COVID-19 outcomes." (PMID 38608066, 2024). "BMI, ADAMTS13 activity, and COVID-19 outcomes were assessed." (PMID 38608066, 2024). "ADAMTS13 activity was measured in 86 hospitalized COVID-19 patients." (PMID 38608066, 2024). "Thus, among the whole COVID-19 study population, at least 31 patients (34.4%) developed ADAMTS13 antibodies." (PMID 37380654, 2023). "Severe COVID-19 patients (needed for mechanical ventilation, n = 19) showed the greatest increase in serum vWF levels and decreases in ADAMTS13 activity compared to moderate (needed for high flow oxygen therapy, n = 17) and mild (needed for low-flow oxygen therapy, n = 14) patients." (PMID 36941580, 2023). "NGAL and FGF23 (vascular hypertrophic factor) are high and ADAMTS13 is low post COVID-19 sequelae." (PMID 38077924, 2023). "Autoantibodies to ADAMTS13 have rarely been investigated in the context of COVID-19 so far." (PMID 37380654, 2023).
COVID-19 (continued). "Plasma exchange could be a therapeutic option for critically ill COVID-19 patients in order to restore the disbalance in the ADAMTS13-vWF axis." (PMID 36979908, 2023). "In addition, serum ADAMTS13 activity tended to negatively correlate with COVID-19 severity, with the greatest decreases in serum ADAMTS13 activity being found in deceased patients." (PMID 36941580, 2023). "Thus low ADAMTS13 levels are correlated with higher risk of TMA and poor outcome in COVID-19 patients." (PMID 37074264, 2023). "Interestingly, the ratios of plasma VWF antigen to ADAMTS13 antigen were significantly higher in patients with severe or critical COVID-19 than in those with mild to moderate disease." (PMID 38002786, 2023). "In addition, an imbalance between vWF and ADAMTS-13 i.e., elevated levels of vWF and decreased levels of ADAMTS13, has been shown to cause ARDS associated with COVID-19." (PMID 38069327, 2023). "This points to the possibility that miR-1228-5p might be involved in an activation of ADAMTS-13 in COVID-19 ARDS." (PMID 36776845, 2023). "Patients receiving haemodialysis with severe COVID-19 had lower ADAMTS-13." (PMID 37175942, 2023). "However, decreased ADAMTS-13 activity and elevated C5b-9 levels have been reported in patients with COVID-19." (PMID 37175680, 2023). "ADAMTS13 antibodies occurred in 31 (34.4%) COVID-19 patients." (PMID 37380654, 2023). "In moderate and severe COVID-19, low ADAMTS-13 levels (below referral) were detected most often." (PMID 35887770, 2022). "Thus, COVID-19 is characterized by a decrease in the concentration and activity of ADAMTS-13 metalloproteinase, especially in patients with the severe form of COVID-19." (PMID 35887770, 2022). "Notably, the increased vWF to ADAMTS13 ratio was accentuated in COVID-19 patients with a fatal outcome." (PMID 35242762, 2022). "Thus, the analysis of the vWF/ADAMTS-13 ratio makes it possible to predict the course of COVID-19 when a patient is admitted to a hospital and can also be a useful tool for monitoring the severity of the disease." (PMID 35887770, 2022). "The presence of anti-ADAMTS-13 antibodies may also decrease ADAMTS-13 activity in COVID-19 patients." (PMID 35887770, 2022). "Overall, treatment of COVID-19-related TMA was directed by the underlying pathophysiology of the disease, with the main recognized mechanisms of TMA in patients with COVID 19 being complement-mediated disease and acquired ADAMTS13 deficiency." (PMID 36232608, 2022). "Elevated levels of established risk factors for thrombosis, in particular elevated levels of VWF and decreased levels of ADAMTS-13 which suggests endothelial activation, may be considered in the treatment of COVID-19." (PMID 35482749, 2022). "The presence of antibodies to ADAMTS-13 may also contribute to the decrease in ADAMTS-13 activity in patients with COVID-19 of varying severity." (PMID 35887770, 2022). "At the same time, there was an increase in ADAMTS-13 inhibitor in patients with mild COVID-19." (PMID 35887770, 2022). "In this study, we looked closely at the role of vWF and ADAMTS-13 in COVID-19." (PMID 35887770, 2022). "On the basis of differentiated clinical and laboratory parameters (renal function tests, coagulation tests, ADAMTS13 levels, PLASMIC score, and detected complement abnormalities), COVID-19-associated aHUS is somewhat more common in the literature published to date." (PMID 36232608, 2022). "When compared to controls, COVID-19 patients had significantly lower concentrations of ADAMTS13 and albumin (ALB) but higher M30, M65, α1-acid glycoprotein (AGP), α1-antitrypsin (AAT), ceruloplasmin (CP), haptoglobin (HP), and high-sensitivity C-reactive protein (hs-CRP)." (PMID 36514048, 2022). "At point 2, ADAMTS-13 activity decreased as the COVID-19 severity increased." (PMID 35887770, 2022). "Small-scale studies have also shown decreased ADAMTS13 levels secondary to COVID-19 inflammation." (PMID 35997402, 2022).
COVID-19 (continued). "We also found significantly lower levels of ADAMTS13 in COVID-19 patients relative to controls." (PMID 36514048, 2022). "In conclusion, COVID-19 may present with low ADAMTS13 activity in a subset of hospitalized patients." (PMID 33709050, 2021). "The VWF/ADAMTS-13 fraction may be a helpful tool to monitor COVID-19 patients throughout hospitalization." (PMID 34573989, 2021). "In summary, we present the most comprehensive and largest study to date analyzing correlations of D-dimer levels with VWF activity and antigen, size of VWF multimers, ADAMTS13 activity levels, markers of intravascular hemolysis, and smear pathology in hospitalized COVID-19 patients." (PMID 33709050, 2021). "Regarding ADAMTS13 levels in COVID-19 patients, the reports are less consistent." (PMID 34575297, 2021). "We evaluated the impact of the VWF/ADAMTS-13 fraction on COVID-19 severity and prognosis." (PMID 34573989, 2021). "Interestingly, the vWF/ADAMTS13 axis is directly investigated in the context of COVID-19-related VTE." (PMID 34564316, 2021). "Along with NETs, VWF and ADAMTS13 are also reported to be involved in COVID-19." (PMID 33343584, 2020). "According to these criteria, we found four procoagulants (ADAMTS13, F11, HGFAC, KLKB1) and two anticoagulants (C1QTNF1, SERPINA5), whose expression may predispose males and older individuals to COVID-19-related coagulopathy and severe COVID-19 disease." (PMID 32751741, 2020). "Indeed, several studies have shown that plasma of COVID-19 patients with microangiopathy contains low ADAMTS13 activity and increased vWF and factor VII levels." (PMID 33357215, 2020). "Another study revealed a significant increase in vWF activity and decreased ADAMTS-13 levels in COVID-19 patients, suggesting that impaired regulation of vWF and the reduced capacity of its cleavage by ADAMTS-13 could be indicative of an increased thrombosis risk." (PMID 40612950, 2025). "Additionally, a study of 50 patients at least 6 weeks post-infection with COVID-19 showed plasma ADAMTS13 levels were significantly reduced when compared to healthy controls (Lower limit of normal local reference for the study 399 ng/mL [Median 598 ng/mL vs. 630 ng/mL, p = 0.009])." (PMID 39274365, 2024). "Different miRNA signatures have been shown in critically ill COVID-19 patients as opposed to hospital-ward-treated patients, including altered miR-16-5p and miR-192-5p expression, which have been shown to associate with platelets and ADAMTS13, respectively." (PMID 39237986, 2024). "However, TTP’s clinical features may appear in some COVID-19 cases with normal or slight decrease of ADAMTS-13 levels." (PMID 38327640, 2024). "However, to the best of our knowledge, ours is the first study assessing the potential contribution of a set of single nucleotide polymorphisms in the vWF and ADAMTS13 genes, key factors in the background of CAC, to increased thrombotic risk among COVID-19 patients." (PMID 36980889, 2023). "Thus, a dysregulation of ADAMTS-13 in COVID-19 could lead to increased VWF activity, thereby fostering the microvascular thrombosis." (PMID 38077924, 2023). "Patients with the clinical picture of COVID-19-associated TTP were characterized by lower platelet counts (median platelets count in patients with TTP was 14, range 5–100, compared to 36, range 6–157, in aHUS) and very low ADAMTS13 activity (<10% in all cases)." (PMID 36232608, 2022). "In addition to increased levels of pro-coagulant factors, thrombotic complications reported in COVID-19 patients may also arise for impaired endogenous anticoagulants, including Protein C and ADAMTS13." (PMID 34834519, 2021). "However, normal ADAMTS13 activity was also observed in COVID-19 inpatients." (PMID 33343584, 2020). "In addition, the levels of VWF and ADAMTS13 can predict the mortality of COVID-19." (PMID 33343584, 2020).
COVID-19 (continued). "Moreover, the publication of COVID-19-associated TMA case reports and studies suggesting a possible role of ADAMTS-13 in the pathogenesis of SARS-COV-2 may have raised awareness, potentially increasing referrals for ADAMTS-13 activity testing." (PMID 40993743, 2025). "However, we cannot rule out that COVID-19 could predispose individuals to TTP through mechanisms such as ADAMTS-13 antibody generation." (PMID 40993743, 2025). "Coagulopathy in COVID-19 is characterized also by elevated levels of factor VIII and von Willebrand factor (vWF) and decreased ADAMTS13 activity." (PMID 39457048, 2024). "ADAMTS13, a Disintegrin And Metalloproteinase with A Thrombospondin Motif 13, cleaves VWF multimers, and low levels have been shown in COVID-19 as well as other inflammatory conditions." (PMID 39237986, 2024). "In a nutshell, the interaction between fibrin(ogen), D-dimer, P-selectin, VWF, and biomarkers like MMPs, ADAMTS-13, renal NGAL, PUMP, and TMPRSS2 intertwine within the context of acute COVID-19." (PMID 38077924, 2023). "In summary, the interaction between fibrin(ogen), D-dimer, P-selectin, VWF, and the mentioned biomarkers like MMPs, ADAMTS-13, renal NGAL, PUMP, and TMPRSS2 intertwines within the context of acute COVID-19." (PMID 38077924, 2023). "ADAMTS13 and VWF are inappropriately regulated in SCD, similar to what is seen in COVID-19 patients." (PMID 37159776, 2023). "We performed plasma exchange in 25 critically ill COVID-19 patients with acute respiratory distress syndrome, leading to a significant decrease in VWF:Ag and increased ADAMTS13 activity." (PMID 37380654, 2023). "We found a significant positive genetic correlation of VTE with COVID-19 hospitalization and identified specific shared loci for VTE with each COVID-19 trait in ABO, ADAMTS13 and FUT2 genes, which was involved in coagulation." (PMID 37085521, 2023). "Increased levels of vWf, Ang-II, and P-selectin and a decreased activity of Willebrand factor-cleaving protease (VWFCP, ADAMTS-13) further highlight endothelial activation in critically ill patients with COVID-19." (PMID 37834324, 2023). "Median ADAMTS13 activity was 67.5%, IQR 28.5, in COVID-19 patients vs. 75.5%, IQR 22.5, in healthy controls (p=0.017)." (PMID 37380654, 2023). "It is known that COVID-19 patients experienced significantly increased levels and function of vWF together with increased FVIII clotting activity, while ADAMTS13 activity slightly decreased." (PMID 37092518, 2023). "Subsequently, the VWF:AG/ADAMTS13 activity ratios in COVID-19 (+) patients (Median:6.051 and IQR:3.824–10.17) were significantly higher (p < 0.0001) than COVID-19 (−) patients (Median:5.567 and IQR:3.352–8.245)." (PMID 35087853, 2021). "There is evidence that, in COVID-19 patients, the increase in VWF levels coexist with a moderate reduction in ADAMTS13 activity." (PMID 34977191, 2021). "This relationship was significant in both groups (ICU: p = 0.006; MW: p = 0.02).Conclusions: The present findings show that in COVID-19, the VWF/ADAMTS-13 fraction predicts in-hospital mortality." (PMID 34573989, 2021). "In this review, we summarize the biological characteristics and interactions of NETs, VWF, and ADAMTS13, and discuss their roles in TMAs, AIS, and COVID-19." (PMID 33343584, 2020). "Generally, the proteome of EVs in COVID-19 shows abnormalities, such as complement activation and platelet hyperreactivity, and increased loads of vWF, UPAR, and ADAMTS13 that correlates with higher levels of the thrombotic marker, D-dimer, and increased disease severity." (PMID 38397093, 2024). "The cross-trait and co-localization analyses identify 2, 3, and 4 shared loci between venous thromboembolism and severe COVID-19, COVID-19 hospitalization, SARS-CoV-2 infection respectively, which are mapped to ABO, ADAMTS13, FUT2 genes involved in coagulation functions." (PMID 37085521, 2023). "Furthermore, reduced ADAMTS-13 levels and ultralarge VWF multimers have been observed in severe COVID-19." (PMID 36817284, 2023).
COVID-19 (continued). "Plasma ADAMTS13 activity but not its antigen levels were significantly lower in patients with severe or critical COVID-19 compared with that in other patient groups." (PMID 38002786, 2023). "The corresponding network derived from immune and endothelial cell signaling is considerably smaller than the networks comparing COVID-19 patients to healthy controls and no direct regulatory effects for the glycocalyx components or ADAMTS13 can be identified." (PMID 36776845, 2023). "In adult non-pregnant patients with COVID-19, elevated VWF/ADAMTS-13 ratios were found associated with disease severity, being highest in those with worse illness or in non-survivors." (PMID 35189860, 2022). "We observed a negative correlation of cfDNA with the ADAMTS13:VWF ratio, a marker associated with COVID-19 severity and severe AKI, along with a positive correlation with LDH, ferritin, and haptoglobin, suggesting a picture of a secondary TMA." (PMID 35497096, 2022). "VWF, ADAMTS13, thrombin generation, and plasmin generation characteristics by survivors and non–survivors in COVID-19 positive and negative groups." (PMID 35087853, 2021). "Levels of ADAMTS13, an antithrombotic metalloprotease which cleaves highly adhesive large von Willebrand factor (VWF) multimers after their release from activated endothelium, decreased significantly with increasing COVID-19 severity." (PMID 33058027, 2021). "Nonetheless, this does not diminish the potential relevance of VWF/ADAMTS13 axis parameters, and of plasma thrombin and plasmin generation parameters, regarding the COVID-19 (+) patients evaluated in this study." (PMID 35087853, 2021). "This is relevant given the importance of coagulopathy in COVID-19, with increased plasma levels of FVIII, D-dimers, and VWF (i.e., increased VWF:collagen-binding activity, increased VWF:ADAMTS-13 activity ratio), which are among the top correlates of mortality in our cohort." (PMID 34571942, 2021). "The VWF:AG/ADAMTS13 activity ratio was increased by 32 vs. 23% in COVID-19 (−) and COVID-19 (+) non-surviving patients, respectively." (PMID 35087853, 2021). "Respective median ADAMTS13 antigen and activity levels were 0.806 (IQR:0.592–1.023) and 0.597 (IQR:0.427–0.767) U/mL in COVID-19 (+) and 0.813 (IQR:0.614–1.069) and 0.54 (IQR:0.420–0.689) U/mL in COVID-19 (−) patients." (PMID 35087853, 2021). "Based on our current data with COVID-19 (−) and COVID-19 (+) patients, there was a clear age-dependent effect (i.e., ≥65) on VFW:AG, VWF collagen binding activity, and the VWF:AG/ADAMTS13 activity ratio, suggesting an enhanced potential for endothelial coagulopathy." (PMID 35087853, 2021). "The VWF/ADAMTS13 axis as well as plasma hemostasis and fibrinolysis were compared within the COVID-19 (−) and COVID-19 (+) groups to understand the differences in VWF/ADAMTS13 axis and plasma coagulopathy between surviving and non-surviving patients." (PMID 35087853, 2021). "The interplay among NET, VWF and ADAMTS13 might form a vicious cycle, resulting in reduced ADAMTS13 activity and subsequently elevated plasma levels of VWF, which is positively correlated with severity and mortality in TMAs, AIS, and COVID-19." (PMID 33343584, 2020). "A study of 88 PCR-proven COVID-19 patients demonstrated that COVID-19 non-survivors had significantly lower levels of ADAMTS-13 activity (32.2 iu/dL vs. 50.6 iu/dL, p = 0.035) and higher levels of vWF (395.5 iu/dL vs. 295.5 iu/dL, p = 0.033) when compared to patients who survived." (PMID 39274365, 2024). "Although many reports have demonstrated decreased ADAMTS13 activity and increased von Willebrand factor (VWF) in patients with COVID-19, ADAMTS-13 activity was not less than 10% in COVID-19 and the clinical usefulness of a mild decrease in ADAMTS-13 is not clear." (PMID 37175680, 2023).